APLN (apelin)
Diseases named in the same sentence as APLN in open-access papers (continued):
Sharing a sentence is not in itself a finding about the gene and the disease.
diabetes (continued). "Nowadays, apelin is believed to assist in regulating glucose metabolism, and the apelin–APJ system has been demonstrated to be related with diabetes mellitus and diabetic complications." (PMID 35355561, 2022). "A previous research reported that the apelin–APJ system reduces vasodilatation and increases vasoconstriction in insulin resistance-related disorders, such as diabetes and cardiovascular dysfunction." (PMID 35355561, 2022). "In this study, the role of apelin and its receptor APJ in endothelial dysfunction induced by diabetes mellitus and following diabetic cardiomyopathy were investigated in diabetic animal models." (PMID 33504680, 2021). "Serum levels of apelin and TNF-α were higher in patients with diabetes than those in the NC group, as well as in the DPN group as compared to the non-DPN group; furthermore, some NCV values were significantly reduced in the DPN group." (PMID 33907154, 2021). "Disruption in the apelin/APJ system resulted to decrement vasodilatation and improved vasoconstriction responses described in diabetes and cardiovascular dysfunctions." (PMID 32908933, 2020). "Apelin serum level, APJ and apelin gene expression in adipose tissue increased significantly with the development of diabetes compared to the control group." (PMID 33278072, 2020). "In conclusion, this study demonstrated that there was a close relationship among Apelin-13, BMD, ICTP and PINP, and Apelin-13 plays an important role in the occurrence of osteoporosis in patients with Type-2 diabetes mellitus." (PMID 29643899, 2018). "However, hypothalamic apelin could lead to deleterious effect for liver with diabetes." (PMID 29340118, 2017). "OP and DPN shared long diabetes duration, high FGF23, and low Apelin-13." (PMID 42200082, 2026). "The effect of specific diabetes treatments on apelin and DKD has not been directly studied, but insights into their potential role have emerged from studies of other pathologies." (PMID 41515992, 2025). "In this review, we summarize the most recent literature on apelin and its cellular mechanisms of action, highlighting the role of the apelinergic system in various pathologies and its impact on patients with CKD and diabetes." (PMID 41515992, 2025). "Visfatin and apelin may also be involved in the induction of β-cell proliferation in vitro and in rats in HFD and STZ models of diabetes." (PMID 39045459, 2024). "Apelin is an adipokine that is the ligand for the G protein-couple receptor APJ and has been of focus due to its sensitivity to glucose homeostasis and link to diabetes and insulin resistance." (PMID 38764585, 2024). "This reviewsummarizes the potential roles of myokines such as myostatin, irisin,brain-derived neurotrophic factor, mitsugumin 53, meteorin-like, and apelin invarious CVD, including myocardial infarction, heart failure, atherosclerosis,hypertension, and diabetes." (PMID 39077334, 2024). "At the same time, other authors have reported surprisingly low levels of apelin in a group of obese individuals with newly diagnosed T2DM compared to healthy individuals without diabetes." (PMID 38203346, 2023). "After 2 months of diabetes, femoral artery ligation was performed in nondiabetic and diabetic mice receiving or not systemic delivery of Pyr-apelin-13 with subcutaneous osmotic pumps." (PMID 37636297, 2023). "However, to our knowledge, no study has investigated the impact of the apelinergic system (apelin/APJ axis) on angiogenesis under the combination of limb ischemia and diabetes." (PMID 37636297, 2023). "Subgroup analyses based on medical comorbidities of diabetes/MetS revealed that apelin levels were significantly lower in CVD patients without diabetes and MetS than in the controls." (PMID 35913970, 2022).
diabetes (continued). "Multivariable logistic regression analysis was performed to investigate the risk factors of MCI in T2DM patients, including education levels (years), diabetes duration (years), the presence of CVD, serum HbA1c, HDL-C, creatinine, BDNF and apelin (OR = 0.304, 95%CI = 0.104–0.886; P = 0.029)." (PMID 35610700, 2022). "After treatment, the serum levels of apelin, TNF-α, and FBG reduced in patients with diabetes; moreover, apelin levels were found significantly lower in the DPN-B group as compared to the DPN-A group, while some NCV values significantly increased in the DPN-B group." (PMID 33907154, 2021). "Therefore, the purpose of this study was to investigate the relationship between the serum level of Apelin-13 and BMD as well as other parameters, and determine the influence of Apelin-13 on osteoporosis in patients with Type-2 diabetes mellitus." (PMID 29643899, 2018). "So far, the direct link between APLN and Sirt3 in the regulation of myocardial angiogenesis in post-MI diabetes has not been reported." (PMID 25311234, 2015). "Consistent with these, our co-localization of vWF and TUNEL data suggested a potential involvement of apelin gene therapy on cardiomyocyte apoptosis, but not EC in ischaemic heart of diabetes." (PMID 25311234, 2015). "Gender, drugs (renin-angiotensin-aldosteron inhibitors, statins), presence of left ventricular hypertrophy, diabetes mellitus, hypertension, hyperlipidemia and significant residual renal function did not affect apelin-36 levels." (PMID 24433492, 2014). "Since apelin has been recognized as a factor contributing to diabetes and cell proliferation, and having not been investigated in DR, we propose a putative role for apelin in promoting proliferation in the retinas of those with DR." (PMID 23874984, 2013). "In our previous study, we found that the concentration of apelin is higher in the vitreous of patients with PDR than in patients without diabetes." (PMID 23874984, 2013). "The current study genotyped three tagging SNPs of APLN region in a Chinese population with and without diabetes." (PMID 23316219, 2012). "The aim of the study was to investigate the association between the common variants of apelin gene (APLN) and hypertension, which was reported recently in a Chinese Han population with and without diabetes." (PMID 23316219, 2012). "A detailed history was taken for the duration and complications of diabetes, and samples were drawn for fasting and postprandial blood sugar levels, HbA1c, LFT (liver function test) and KFT (kidney function test), lipid profile, serum fasting insulin levels, and serum apelin levels." (PMID 42211608, 2026). "Various hormone-like molecules (adiponectin, leptin, resistin, apelin, visfatin, adipsin, omentin, chemerin, and metrnl) are classified as adipokines that are produced by WAT and play a multifaceted role in numerous diseases, including diabetes, atherosclerosis, CVD, and immune disorders." (PMID 39538244, 2024). "An increase in apelin (i.e., raised to levels between 1.63–3.52 ng/mL) may lead to improved vasodilation, heart contractility, GLUT 4 activity and energy metabolism in overweight, hyperlipidemia and diabetes patients." (PMID 36833129, 2023). "Also, the serum level of Apelin-13 in people with PDR is significantly higher compared to diabetics without PDR16." (PMID 37828117, 2023). "Also, maternal plasma apelin levels have been reported to be significantly higher in patients with gestational diabetes compared to pregnant women without diabetes, which is positively correlated with their umbilical cord blood levels." (PMID 36093083, 2022). "However, further analysis showed that the presence of hypertension and diabetes or not did not affect apelin levels in patients with OHCM." (PMID 35783816, 2022). "Nevertheless, the level of apelin in pregnancy with and without diabetes is controversial." (PMID 36093083, 2022).
diabetes (continued). "It is reported that apelin might decrease apoptosis and the expression of adhesion molecules and increase proliferation and angiogenesis via APJ-activated NF-κB pathways, finally resulting in the protection of diabetes-induced endothelial dysfunction." (PMID 35355561, 2022). "In addition, levels of apelin are higher in obese subjects without diabetes than in obese patients with T2D." (PMID 35628332, 2022). "In addition, apelin content was lower in the COVID-19 and COVID-19 + diabetes mellitus groups compared to the non-COVID-19 counterpart groups." (PMID 36352477, 2022). "Apelin and its receptor, AJP, are extensively distributed in heart and the vascular tissues, both of which involve in various pathological processes, especially in the cardiovascular disorders, diabetes complicated with micro-vascular diseases and the ischemia reperfusion injuries." (PMID 33342766, 2020). "Similarly, IPA for “canonical pathways” identified pattern recognition, apelin cardiomyocyte signaling, white adipose tissue browning, SNARE signaling, complement system, PPARα, RxR α activation, IL-8 signaling, NAD homeostasis and CLEAR signaling as enriched in diabetes." (PMID 36902363, 2023). "Moreover, apelin was significantly lower in patients without diabetes/MetS." (PMID 35913970, 2022). "Decreased apelin concentration in COVID-19 patients may be one of the reasons for the disturbances in blood glucose regulation in these patients, even in those who are without diabetes mellitus." (PMID 36352477, 2022). "Icariin has a cardioprotective effect in high-glucose-treated cardiomyocytes via upregulating apelin and SIRT3 expression, which can reverse diabetes-induced mitochondrial dysfunction; however, it did not affect the activity of SIRT3 in apelin silence samples." (PMID 35355561, 2022). "No significance was reached for apelin gene in females and for APJ gene in both genders, even after controlling age, type 2 diabetes mellitus, BMI and SBP." (PMID 23226564, 2012). "Recent clinical studies have identified apelin-13 as a potential biomarker in patients with CKD, suggesting a compensatory increase in response to renal impairment and cardiovascular disturbance regardless of the presence of diabetes." (PMID 40177358, 2025).
heart failure (90 papers, 2008 to 2026). Inability of the heart to pump blood at an adequate rate to meet tissue metabolic requirements. "In particular, we look at myostatin and irisin in the context of the development of heart failure and decreased levels of apelin with higher cardiovascular risk in a group of patients with rheumatoid arthritis." (PMID 40943120, 2025). "Third, apelin improves cardiac function in conditions of heart failure frequently caused by ACS by increasing cardiac output and decreasing blood pressure and peripheral vascular resistance." (PMID 41198895, 2025). "Apelin is a cardioprotective peptide, and its loss contributes to systolic dysfunction and heart failure." (PMID 38892464, 2024). "As such, apelin has been implicated in the pathogenesis of numerous diseases, such as obesity, diabetes, hypertension, cardiac hypertrophy, and heart failure." (PMID 37111357, 2023). "In our observation, the lower levels of apelin-13 and higher levels of oxidative stress are associated with higher NT-proBNP levels, more severe heart failure, and unfavourable outcome during the follow-up." (PMID 34257745, 2021). "In humans, it was shown that apelin administration caused peripheral and coronary vasodilatation, and increased cardiac contractility in patients with heart failure." (PMID 32708358, 2020). "In heart failure patients, intracoronary [Pyr1]apelin-13 caused coronary vasodilatation and increased cardiac contractility." (PMID 28293165, 2017). "Although the underlying signaling mechanisms remain to be explored, apelin deficiency in chronic pressure overload resulted in severe heart failure characterized by LV dilation and impaired cardiac performance." (PMID 24695532, 2014). "Conversely, downregulation of Apelin has been linked to heart failure and ventricular dysfunction." (PMID 34364390, 2021). "Importantly, pressure overload- induced heart failure is also more severe in apelin-deficient mice." (PMID 34880830, 2021). "In terms of heart failure, cardiac apelin expression has been shown to be reduced in experimental left ventricular hypertrophy and heart failure comprising Dahl salt-sensitive rats, which was reversed by treatment with the AT1receptor blocker telmisartan." (PMID 41515891, 2025). "In heart failure patients, intravenous administration of apelin increased cardiac output and left ventricle ejection fraction while reducing vascular resistance." (PMID 41155377, 2025). "While the beneficial results of Elabela are somewhat predictable based on the ability of apelin to reduce hypertrophy and heart failure via APJ activation, it is interesting that some differences between Elabela and apelin have been reported." (PMID 41515891, 2025). "Apelin is an important regulator of cardiac and skeletal muscle homeostasis, and its absence leads to premature cardiac failure and sarcopenia." (PMID 40801027, 2025). "With the growing understanding of the role of the apelin–ELA–APJ system in heart failure pathophysiology, it is increasingly seen as a potential therapeutic and diagnostic target." (PMID 41155377, 2025). "Systemic administering of apelin has been shown to reduce peripheral vascular resistance and blood pressure in both healthy subjects and in those with heart failure, even while the renin–angiotensin system is activated." (PMID 40943120, 2025). "Apelin plays important role in pathologies such as hypoxia-related diseases and heart failure, in which it shows a cardioprotective effect by defending the myocardium against infarction." (PMID 41198895, 2025). "The apelinergic system is involved in the pathogenetic processes of heart failure, with plasma apelin levels increasing in the early stages of heart failure but decreasing in more advanced ones." (PMID 41155377, 2025). "Apelin is a peptide hormone with cardioprotective effects, but it undergoes compensatory up-regulation in heart failure." (PMID 41226290, 2025).
heart failure (continued). "Two prospective studies on patients with T2D and heart failure found that treatment with dapagliflozin increased circulating apelin levels." (PMID 41515992, 2025). "Apelin can also produce beneficial effects through its positive inotropic influence and afterload reduction, and clinical studies have shown that apelin-13 infusion improves cardiac function in heart failure patients." (PMID 41515891, 2025). "It has been demonstrated that BMS-986224 has physiological effects similar to those of [Pyr1]-apelin-13, and it has shown a promising therapeutic potential in preclinical models of heart failure." (PMID 41515992, 2025). "Based on numerous positive results using apelin in heart failure models, the peptide shows promise as a potential therapeutic agent, although its effectiveness is limited by a short in vivo half-life of less than 5 min." (PMID 41515891, 2025). "Apelin is an endogenous peptide recognized for its therapeutic potential in hypertension and heart failure, as well as for its modulation of the endocrine system." (PMID 40141374, 2025). "Apelin isoforms were found to protect against conditions like ischemia, heart failure (HF), and myocardial infarction." (PMID 39335642, 2024). "Of noteworthy significance, Apelin emerges as a well-established therapeutic target for a spectrum of conditions encompassing hypertension, atherosclerosis, myocardial infarction, and heart failure." (PMID 39411402, 2024). "Meanwhile, studies carried out in heart failure patients, as well as the findings of a mouse model of atherosclerosis, showed that apelin reduced blood pressure, acutely so in heart failure subjects." (PMID 39457235, 2024). "In rats with myocardial infarction-induced heart failure, apelin inhibits fibrosis and PI3K/Akt activity via the TGF-β1/smad 2 pathway to reduce oxidative stress." (PMID 36871006, 2023). "Although there is an initial rise in circulating apelin, expression is reduced in later-stage heart failure." (PMID 36239923, 2023). "It is believed that apelin plays a protective role in cardiovascular diseases, such as heart failure and hypertension." (PMID 37111357, 2023). "Intravenous infusion of Pyr1-apelin-13 increased the cardiac index, lowered BP, and reduced peripheral vascular resistance in control subjects and patients with heart failure." (PMID 36986889, 2023). "The amino acid apelin raises intracellular Ca2+ concentration, which in turn boosts cardiac output, in heart failure patients, and has a remarkable inotropic effect that is beneficial to the heart." (PMID 36871006, 2023). "Intravenous infusion of Pyr1-apelin-13 induced forearm vasodilation in patients with heart failure and control subjects." (PMID 36986889, 2023). "Evidence from animal study indicated that exogenous administration of apelin improved LV systolic function in dogs with advanced heart failure." (PMID 35783816, 2022). "Recent studies have shown that apelin has diverse protective effects in many cardiovascular diseases, such as heart failure, systemic and pulmonary arterial hypertension and ischemic-reperfusion lesion." (PMID 35783816, 2022). "In a rodent model of heart failure, infusion of angiotensin II downregulated cardiac apelin expression and this was prevented by blockade of the angiotensin II type 1 receptor." (PMID 35748053, 2022). "Our group has previously shown apelin infusion increases forearm blood flow in patients with heart failure." (PMID 35748053, 2022). "The patients with NYHA IV heart failure and lower ejection fraction had significantly higher levels of NT-proBNP and ACE2 and significantly lower levels of apelin-13 compared to the patients with NYHA II heart failure." (PMID 34257745, 2021). "In heart failure patients, acute administration of apelin, by intravenous route, increases cardiac output and left ventricular ejection fraction while reducing blood pressure and vascular resistance." (PMID 34880830, 2021).